IL6 (interleukin 6)
Diseases named in the same sentence as IL6 in open-access papers (continued):
Sharing a sentence is not in itself a finding about the gene and the disease.
leiomyoma (10 papers, 2018 to 2026). A well-circumscribed benign smooth muscle neoplasm characterized by the presence of spindle cells with cigar-shaped nuclei, interlacing fascicles, and a whorled pattern. "A significant decrease in IL-1β and IL-6 was observed in the endometrium of women with fibroids, alongside a notable increase in cyclooxygenases COX1, COX2, and VEGF." (PMID 40672945, 2025). "Chegini reported that IL-6 increases proliferation and fibrotic response in leiomyoma cells via STAT-3." (PMID 40943781, 2025). "Although IL6, TNF-α, IFN-γ, G-CSF, and TGF-β1, which have been implicated in leiomyoma development, were expressed in both cell types, the most notable finding was the significantly different expression of Th2 and Th1/Th17 pathways in LPCs and MPCs." (PMID 29861738, 2018). "Major cytokines, namely the expression of interleukin 1 (IL1), 6 (IL6), 11 (IL11), 13 (IL13), 15 (IL15), 33 (IL33), tumor necrosis factor α (TNFα), and the granulocyte-macrophage colony-stimulating factor, have been implicated to leiomyoma pathophysiology." (PMID 34442017, 2021). "Leptin induces a tumor-friendly microenvironment through upregulation of pro-inflammatory (IFNγ, IL-8, IL-6, GM-CSF, MCP-1, and TNF-α), fibrotic (TGF-β1, TGF-β2, and TGF-β3), and angiogenic (VEGF-A, HGF, and Follistatin) factors in human leiomyoma cells." (PMID 36771423, 2023). "Our study found that leptin treatment of leiomyoma cells increased pro-inflammatory factors, MCP-1, IFNγ, IL-8, GM-CSF, IL-6, and TNF-a." (PMID 36771423, 2023). "Numerous studies described leiomyoma cells exhibiting a significantly greater expression of IL1, IL4, IL5, IL6, IL10, IL11, IL13, and IL15." (PMID 34442017, 2021). "A total of eight leiomyoma-related DEGs (EGR1, CEBPB, IL6, PECAM1, VWF, TNFRSF1A, CD34 and ACE) were found upregulated in MF versus M only." (PMID 33807176, 2021). "The decrease of TGFβ, IL6, and IL10 immunoexpression, as well as the macrophage and mast cell infiltration in fibroids, observed in cases of a good response to the UPA treatment may be an important component of the total effect of UPA on uterine fibroid tissue." (PMID 34442017, 2021). "Elevated IL-6/TNF-α occurred only in patients with EIN/EC (total of 23%), while no abnormalities were observed in the leiomyoma group." (PMID 41595367, 2026).
mastocytosis (10 papers, 2016 to 2025). A clonal myeloproliferative neoplasm characterized by the proliferation and accumulation of neoplastic mast cells in one or multiple organs or organ systems. "Or perhaps the overall effect of targeted blocking of IL-6 in mastocytosis is minimal considering the complexity of the underlying pathologic processes and the influence of many other elevated inflammatory mediators." (PMID 40529483, 2025). "We propose consideration of IL-6 blockade as a potential adjunctive therapy in the treatment of patients with advanced mastocytosis, as it would reduce DJ-1 levels making mutation-positive mast cells vulnerable to oxidative damage." (PMID 27611333, 2016). "We have unpublished data from another mastocytosis patient who lost consciousness within minutes of an attack with 126 and 424 pg/ml IL-6 plasma concentrations 2 h after the first symptoms indicating storage of IL-6 in mast cells." (PMID 40299000, 2025). "IL-6 is produced by MC, and patients with mastocytosis have increased IL-6 plasma levels probably related to the constitutional activation of the KIT signaling pathway caused by D816V mutation, as described in in vitro models." (PMID 37108232, 2023). "A hypothetical model for generation of fatigue in mastocytosis is therefore thatactivated MCs outside the brain release IL-1β, IL-6, TNF-α, and other bioactivemolecules that pass the BBB and activate neuronal cells as well as microglia." (PMID 30350746, 2018). "From this perspective, our data are consistent with the reported view of IL-6 over-production as a key factor favoring progression of mastocytosis into more advanced disease." (PMID 27611333, 2016). "A mouse model of mastocytosis recapitulated the biphasic changes in DJ-1 and the escalating IL-6, ROS and DJ-1 levels as mast cells accumulate, findings which were reversed with anti-IL-6 receptor blocking antibody." (PMID 27611333, 2016). "IL-6 was of interest because serum IL-6 levels in mastocytosis correlate with tryptase and elevated IL-6 is a better predictor than other cytokines for disease progression." (PMID 27611333, 2016). "Further, in patients with mastocytosis in our cohort, IL-6 levels significantly correlated with the levels of DJ-1." (PMID 27611333, 2016). "Nevertheless, IL-6 concentrations can be rapidly measured and if they are highly elevated, tocilizumab administration might benefit other mastocytosis patients during severe MCA attacks." (PMID 40299000, 2025). "Interleukin 6 is a major MC-derived mediator and is elevated in patients with mastocytosis." (PMID 33401724, 2021). "Consequently, other mastocytosis patients with highly elevated IL-6 concentrations during severe MCA events might also benefit from a single administration of tocilizumab." (PMID 40299000, 2025). "Therefore, IL-6, although not specific for MC, can be considered a good diagnostic and prognostic biomarker of the severity of mastocytosis." (PMID 37108232, 2023). "In addition, increased IL-6 serum levels correlated with severity of symptoms, the SCORMA (SCORing MAstocytosis) index, disease progression, and the presence of osteoporosis." (PMID 33401724, 2021).
melancholic depression (10 papers, 2017 to 2026). "Melancholic depression is also characterized by increased IL-6 and sIL-6R (enhanced IL-6 trans-signaling) and decreased IL-1α and TGF-β." (PMID 33255237, 2020). "Further studies specified that enhanced IL-6 trans-signaling is characteristic of an acute (current) depressive episode (melancholic or atypical) compared to a remitted state and is a distinctive feature of TRD and melancholia." (PMID 33255237, 2020).
metastasis (10 papers, 2017 to 2025). The spread or migration of cancer cells from one part of the body (where they first appeared) to another. "Moreover, a study on a northwest Iranian population has reported that IL-6 rs1800795 (-174, G/C) SNP represents a good predictor for PCa susceptibility and bone metastasis as it was concomitant with increased IL-6 production and PCa risk." (PMID 34327025, 2021). "We verified the impact of primary tumour size, the status of lymph node metastasis, distant metastasis, and the grading of histological malignancy on the methylation level of the IL-6 promoter region." (PMID 37047238, 2023). "However, the incidence of lung/liver metastasis at baseline was neither associated with baseline IL-6 or CRP levels nor with the best response to chemotherapy." (PMID 35965580, 2022). "Moreover, we have validated some previously reported overexpressed genes such as TGFB1, IBSP, MMP9, or ITGB3 in bone metastasis; CRYAB, NRCAM, and SOX2 in brain metastasis; VEGF and IL6 in lung metastasis; and CYP4F3 in liver metastasis." (PMID 34051058, 2022).
nephrotic syndrome (10 papers, 2011 to 2025). A collection of symptoms that include severe edema, proteinuria, and hypoalbuminemia; it is indicative of renal dysfunction. "Recently, several reports have suggested that excessive IL-6 actions in iMCD could have a causal relationship with the development of diverse histopathological renal manifestations that cause nephrotic syndrome." (PMID 36698794, 2023). "The results showed that the serum levels of cholesterol, triglyceride, TNF-α, and IL-6 in rats with nephrotic syndrome were increased and the gene and protein expressions of AQP2 and AVP were up-regulated in rats with adriamycin injected into caudal vein." (PMID 36678585, 2023). "Other cytokines, namely, interleukin-1ß (IL-1ß) and interleukin-6 (IL-6), were elevated in patients with nephrotic syndrome compared to controls." (PMID 26989679, 2016). "Lower IL-6 levels could suggest immune dysregulation or suppression related to nephrotic syndrome or its treatment, potentially affecting oral disease progression and systemic inflammatory responses." (PMID 40243946, 2025). "In a few studies, serum IL-6 and IL-17 were found to be elevated while MCP-1 was normal in nephrotic syndrome." (PMID 38127456, 2024). "Previous studies have shown that the expressions of Proinflammatory cytokines, IL-6 and TNF-α, both increase in nephrotic syndrome." (PMID 21822358, 2011).
neuritis (10 papers, 2013 to 2024). A neuropathy arising from inflammation of one or more nerves. "This phenomenon increases neuritis, especially interleukin-like inflammatory factors, such as IL-6, which play a great role and should be considered in future studies." (PMID 37218868, 2023). "For example, flavanone glycosides extracted from citrus fruits can reduce the levels of IL-1β and IL-6 in patients with neuritis." (PMID 36467557, 2022). "IL‐6, a pleiotropic proinflammatory factor, plays an important role in chronic inflammation and neuritis; TNF‐α is also involved in the inflammatory response by inducing NF‐κB activation." (PMID 29670828, 2018). "Excessive activation of microglia is profoundly implicated in the neuroinflammation via producing a cascade of inflammatory mediators such as iNOS/NO, IL-1β, IL-6, and TNF-α, which further result in neuritis, immune response, damage of neurons, and cause cognitive dysfunction." (PMID 34485533, 2021). "Experimental studies corroborate this theory, showing that in the presence of a traumatic CNS injury, the IL-6 receptor is present in oligodendrocytes and neurons and that IL-6-induced neuritis promotes increased neuronal survival by inducing the production of neurotrophic factors 38,39." (PMID 31433044, 2019). "Koumine inhibits the overexpression of interleukin 6 (IL-6), IL-1, and tumor necrosis factor (TNF) in tumors, showing anti-neuritis effects." (PMID 34885727, 2021). "Together, these data suggest that IL-6 could be involved CB, a specific nerve impairment that is not related either to the cutaneous reactional episodes or neuritis." (PMID 34797866, 2021).
Pain (10 papers, 2012 to 2025). An unpleasant sensory and emotional experience associated with actual or potential tissue damage, or described in terms of such damage. "In this study, we investigated the mechanism of action of PRP gel on peripheral nerve-derived pain, focusing on tumor necrosis factor-α (TNF-α) and interleukin-6 (IL-6), which have recently attracted attention in acute and chronic neuropathic pain." (PMID 40951078, 2025). "This supports previous findings done by our lab, where (using another method) plasma IL-6 levels showed a two-fold elevation in patients suffering from peripheral neuropathic pain, thus indicating systemic low-level inflammation among patients." (PMID 33522900, 2021). "Different types of inflammatory mediators (IFMs) are involved in the development of neuropathic pain including interleukin-6 (IL-6), cyclooxygenase-2 (COX-2), and nitric oxide synthase (NOS)." (PMID 33066162, 2020). "Previous studies have reported that microglial activation induces extensive production of proinflammatory cytokines, such as TNF-α, IL-6, and IL-1β, which are involved in the pathogenesis of neuropathic pain." (PMID 32171293, 2020). "The inflammatory mediators such as interleukin-6 (IL-6), interleukin-8 (IL-8), and tumor necrosis factor-α (TNF-α) released from mast cells play important roles in the inflammation and bladder-associated pelvic pain of IC/BPS." (PMID 33133219, 2020). "The most relevant cytokines observed in PTX-induced neuropathic pain are IL-1β, IL-8, and TNF-α, as well as IL-6, IL-4, and IL-10." (PMID 40006070, 2025). "Increased levels of TNF-α, IL-1β, and IL-6 have been observed both in the DRG and SDH in the spinal nerve ligation model of neuropathic pain." (PMID 23365595, 2012). "It is known that serum levels of proinflammatory cytokines such as IL-1β, IL-6, and TNF-α are significantly upregulated during chronic neuropathic pain and anti-inflammatory cytokines such as IL-10 are significantly downregulated during chronic neuropathic pain state." (PMID 30755780, 2019).
Peptic ulcer (10 papers, 2012 to 2025). The term peptic ulcer refers to acid peptic injury of the digestive tract, resulting in mucosal break reaching the submucosa. "Furthermore, individuals with blood group O was found to had higher risk to peptic ulceration due to an increasing density of colonization of epithelial cells and higher inflammatory responses (release of IL-6, IL-10 and TNF-α) to H. pylori.." (PMID 29088730, 2017). "The local inflammatory cytokine IL-6 primarily activates neutrophils, lymphocytes and monocytes/ macrophages at the inflammatory site in stomach, which in turn initiates different oxidative bursts toxic metabolites and lysosomal enzymes responsible for local tissue damage in peptic ulcer disease." (PMID 32311961, 2020). "Inflammation is a pivotal pathological reaction of ethanol-related peptic ulcer, which is mainly characterized by increased secretion of diverse proinflammatory factors, such as TNF-α, IL-6, and IL-1β, and inhibition of the production of anti-inflammatory cytokines such as IL-10." (PMID 32325708, 2020). "On the other hand, IL-6 and IL-8 serum levels in Helicobacter Pylori infected patients with peptic ulcer disease are not elevated." (PMID 23145841, 2012). "Therefore, the serum levels of IL-6 and TNF-a are closely related to the changes of peptic ulcer." (PMID 33235586, 2020).
Respiratory tract infection (10 papers, 2015 to 2026). An infection of the upper or lower respiratory tract. "Moreover, urinary and respiratory tract infections, and IL-6 levels were independently associated with mortality." (PMID 26649014, 2015). "Primary endpoints were spasticity relief and effective rates; secondary endpoints included improvements in high-amplitude abnormal EEG, IL-6 levels, respiratory tract infection rate, and adverse reactions." (PMID 41908285, 2026). "In summary, in the treatment of inflammation caused by respiratory tract infections, the active components of PRHT play a key role through their synergistic actions with STAT3, TNF-α, and IL-6." (PMID 40456967, 2025). "This is consistent with observations in a study carried out by Mistchenko and co-authors, in which higher IL-6 and TNF-alfa concentrations were found in patients with severe respiratory tract infections caused by HAdVs." (PMID 36649001, 2022). "This higher mortality appears to be related to differences in respiratory tract infection rate and IL-6 plasma levels, between the genders." (PMID 26649014, 2015). "The increased IL-6 level in renal tissue may be due to secondary infection and renal immune complex stimulation, as IgAN often occurs secondary to respiratory tract infection, which increases serum IL-6 levels." (PMID 35870042, 2022). "High concentration of IL-6, TNF-α, and IL-8 were found elevated in other cases of respiratory tract infections in different clinical settings in children (outpatients, inpatients, and intensive care units)." (PMID 33066100, 2020).
retinal ischemia (10 papers, 2013 to 2024). A ischemic disease that involves the retina. "Retinal ischemia increases compensatory angiogenesis, tissue remodeling and inflammation, presumably mediated by elevated expression of IL-6, IL-1β, TNFα and VEGF." (PMID 36983353, 2023). "Previous studies have demonstrated that increased levels of IL-6, IL-8, and monocyte chemotactic protein-1 (MCP-1) in RVO are closely associated with the severity of retinal ischemia." (PMID 30366444, 2018). "Additionally, intracellular adhesion molecules, along with endothelial and glial cells, induce the upregulation of VEGF, TNF-α, IL-6, and IL-1β, leading to retinal ischemia and hypoxia." (PMID 39634174, 2024). "Furthermore, IL-6 has been reported to be upregulated after retinal ischemia and to protect RGCs from ischemic injury." (PMID 24146541, 2013). "Neither IL27 nor IL6 were associated with retinal ischemia, unlike that seen in ONH ischemia." (PMID 34207618, 2021). "Tumor necrosis factor-α (TNF-α), interleukin-6 (IL-6), and adhesion molecules ICAM-1 and VCAM-1 were observed in patients with retinal ischemia." (PMID 28273868, 2017). "Based on routine clinical practice and previous preclinical publications, it is likely that in CRVO with retinal ischemia, VEGF and IL-6 are both higher than in nonischemic CRVO." (PMID 23560031, 2013). "As in whole blood, it has been shown that caffeine does not change the LPS-induced secretion of IL-10, IL-6, and IL-1β, while reduced mRNA expression of IL-6, IL-12, and IL-3 has been found in LPS-activated RAW264.7 cells or retinal ischemia/reperfusion-induced IL-6 and IL-1β secretion by microglia." (PMID 34371919, 2021).
small cell lung carcinoma (10 papers, 2014 to 2025). Small cell lung cancer (SCLC) is a highly aggressive malignant neoplasm, accounting for 10-15% of lung cancer cases, characterized byrapid growth, and early metastasis. "While serum VEGF level in small cell lung cancer patients have been found to correlate with IL-6 and IL-8, VEGF has been found to be associated with WBC in NSCLC patients." (PMID 41509932, 2025). "They suggested that BAL and blood cells from patients with small cell lung carcinoma secreted significantly less cytokines (IL-1, IL-6 and TNF-α) than BAL and blood cells from patients with NSCLC." (PMID 26316944, 2014). "BAL and whole blood cells from patients with small cell lung carcinoma and NSCLC cancer were compared in their secretion of IL-1, IL-6, and TNF-α." (PMID 26316944, 2014). "Prophylactic use of an anti-IL-6 mAb, which is currently used in the management of CRS, is being trialled with CD3xPSMA BiTE for small cell lung cancer (NCT04496674) and may allow an increased maximum tolerated dose of the BiTE." (PMID 37599903, 2023).
soft tissue sarcoma (10 papers, 2012 to 2025). A malignant neoplasm arising from muscle tissue, adipose tissue, blood vessels, fibrous tissue, or other supportive tissues excluding the bones. "Conversely, a high circulating level of interleukin 6 caused by a cytokine storm can lead to abnormal lipid metabolism and muscle loss in mice with soft tissue sarcoma." (PMID 39014376, 2024). "High levels of IL-6 were detected in the serum of soft tissue sarcoma patients and were associated with poor survival." (PMID 37332046, 2023). "Systemic inflammation and high circulating IL‐6 levels are associated with poor prognosis in patients with soft tissue sarcoma." (PMID 36351437, 2023). "Notably, reduced ALC is strongly associated with higher serum concentrations of IL-6 and IL-2 in patients with soft tissue sarcoma." (PMID 41568390, 2025). "In patients with soft tissue sarcomas, elevated circulating levels of IL6 predict the poor prognosis typical of DDLPS." (PMID 35313831, 2022). "Bazedoxifene has been shown to suppress STAT3 activation through IL-6, inhibit tumor growth in a murine model of rhabdomyosarcoma, a soft-tissue sarcoma, and inhibit the proliferation of IL-6 dependent cell lines." (PMID 32765502, 2020). "In fact, decreased ALC significantly correlates with increased serum levels of IL-6 or IL-2 in patients with soft tissue sarcoma." (PMID 31217896, 2019). "This study aimed to elucidate the association between IL-6 and IL-6 receptor (IL-6R) expression in tissues and clinical outcomes in patients with soft tissue sarcomas (STSs) because, to our knowledge, this has not been done before." (PMID 32138303, 2020).